IL6 (interleukin 6)
Diseases named in the same sentence as IL6 in open-access papers (continued):
Sharing a sentence is not in itself a finding about the gene and the disease.
infection (continued). "Interleukin 6 (IL-6) is produced rapidly and transiently in response to infection and tissue damage and contributes to host defense through the stimulation of acute phase responses, as well as hematopoietic and immune responses." (PMID 34959738, 2021). "Serum levels of IL-17a at day 2 post-infection and IL-6, and IL-10 at day 3 post-infection are increased in TLR3+/- compared to CB4-infected wt mice." (PMID 34804036, 2021). "For example, infection with a highly pathogenic influenza virus elevates levels of IFN-γ, IL-1, IL-6, and TNFα in patients." (PMID 34440903, 2021). "Inflammation mediated by UU infection leads to an increase in white blood cells count and inflammatory factors such as IL-8 and IL-6 in newborn blood." (PMID 34956983, 2021). "IL-6 is produced by bladder urothelial cells in response to infection; elevation in IL-6 has been reported in women with OAB." (PMID 33657181, 2021). "Experiments with an Ata knockout strain have indicated that A. baumannii induces host cell secretion of pro-inflammatory cytokines IL-8 during early and IL-6 during later infection stages and monocytes recruitment." (PMID 33922793, 2021). "Exorbitant amounts of TNF-alpha and IL-6 were seen in the peritoneal lavage of mice after KPn infection which peaked at 12 h p.i. in untreated mice." (PMID 34135384, 2021). "Our results revealed that P. multocida experimental infection in rabbits induced significant elevation of serum IL‐6." (PMID 33590677, 2021). "Similar to our findings from the lethal infection model, treatment with L. plantarum resulted in significant reductions in the levels of immunoreactive IL-6, CCL2, and CXCL10 detected in the BAL fluid of mice inoculated with a sublethal dose of PVM." (PMID 34959580, 2021). "Significantly higher secretion of CXCL1/KC, IL-1β, and IL-6 in the mouse lung upon infection with A. flavus conidia also suggest that A. flavus conidia are more efficiently cleared by the host as compared to A. fumigatus conidia." (PMID 33718288, 2021). "We also found that low IL-6–induced STAT1 phosphorylation, or IL-6 hyporesponsiveness, in circulating monocytes and CD8+ T cells is associated with the development of secondary infections in AP." (PMID 34016897, 2021). "The release of pro-inflammatory cytokines, classically IL-1, IL-6, and TNFα, to combat infection has a profound secondary effect on the overall physiologic system that can result in hypotension and tissue damage, as is seen in sepsis." (PMID 33504894, 2021). "We also measured the protein levels of IL-6 in mock- and B.1.351-infected mice at day 3 after infection." (PMID 35062231, 2021). "Specifically, IL-6, IL-1RA and IL-1β were decreased during infection in both therapeutic and preventive groups." (PMID 34112954, 2021). "Surprisingly, early treated individuals exhibited significantly higher IL-6 levels at 12-months post-infection (p=0.036)." (PMID 34630420, 2021). "The pro-inflammatory molecules that increased in the CNS during the infection are most commonly IL-6 and CCL2." (PMID 33917837, 2021). "We noticed increased expression of IL6 mRNA and protein in aggregate positive brain at day 14 of infection." (PMID 34899715, 2021). "IL-6 is induced instantly at the early stages after the infection of monocytes/macrophages, with a subsequent increase in its expression." (PMID 34835417, 2021). "Among all these biomarkers for infection, interleukin 6 (IL‐6) is thought to be more widely used in clinical laboratories." (PMID 34725873, 2021). "As expected, GL or GM pretreatments effectively (P < 0.05) decreased the increased pro-inflammatory cytokines (IFN-γ, TNF-α, and IL-6) induced by ST infection, whereas, they increased anti-inflammatory cytokine IL-10 secretion (P < 0.05)." (PMID 34239908, 2021). "In the early stages of infection, IL-6 is mainly categorized as the pro-inflammatory cytokine (Tilg, Dinarello, and Mier 1997)." (PMID 35173767, 2021).
infection (continued). "When comparison was made between different serotypes and primary/secondary infection, significant difference was observed in cytokines IL-1β, IL-2, IL-6, IL-8, IL-12, TNFα, IFNγ, GM-CSF, and IP-10." (PMID 34447698, 2021). "ELISA quantification of IL-1β, IL-6, and IL-8 in plasma was undetectable in JM-3, A, and JC, as well as in the healthy controls, but they were detected during the acute symptomatic infection in JM (JM-1)." (PMID 34669281, 2021). "On the 2nd day post-infection, E. coli challenge, particularly with E. coli O78, displayed significantly upregulated levels of ileal IL-6 and IL-8, but ileal IL-10 level tended to be downregulated in comparison to the control group." (PMID 34903932, 2021). "FICZ enhanced the expression of il-17, il-22, il-10, and tgf-b mRNAs at both periods but reduced il-6 levels at 96 hours of infection." (PMID 33936043, 2021). "PAR1ΔCF mice exhibited significantly increased CVB3 genome levels, TNF-α mRNA and IL-6 mRNA expression in their hearts 8 days after infection compared with controls." (PMID 34253819, 2021). "IL-6 production in macrophages increased during EPEC ΔNleE infection, compared with WT EPEC infection." (PMID 34254583, 2021). "Changes in the expression of cytokines IL-10, IL-4, IL-6, IL-1β and TNF-α were measured in BALB/c mice, the susceptible host of S. japonicum, and in M. fortis, the resistant host, before infection and on 3, 7, 10 and 14 dpi, respectively." (PMID 34689797, 2021). "IL-1β is an acute phase IL that is produced early in infection and subsequently stimulates the release of IL-6 and IL-8 in mast cells." (PMID 34835359, 2021). "In contrast, a slight IL-4 trigger was observed soon after the infection in the 106 group, while IL-6 and IL-10 increased around two to 10-fold." (PMID 34276650, 2021). "In the context of dengue infections, a study by Lin and colleagues investigated cytokine production by B cells and showed that in vitro infection of B cells by dengue virus (DENV) induced the production of IL-6 and TNF-α." (PMID 34293057, 2021). "C-reactive protein is a marker for infection, increases in response to systemic inflammation and is mainly synthesized by hepatocytes in response to proinflammatory cytokines (IL-1, IL-6, and TNF-α)." (PMID 33937367, 2021). "Of note, cytokines (IL-6 and IL-8) released upon infection of SARS-CoV-2 hamper the ability of T-cells to activate dendritic cells and macrophage and circumvent the adaptive immune response." (PMID 33757410, 2021). "Before the initial infection after the high-fat diet, similarly increased levels of triglycerides, cholesterol, leptin, or IL-6 have been detected." (PMID 33810619, 2021). "Given the implications of these findings, we set out to validate our observations by comparing those three surrogate infection markers against the behaviour of two key urinary cytokines namely IL6 and Lactoferrin, in patients with OAB." (PMID 33740940, 2021). "There was an interaction (p < 0.05) between probiotics and infection for IL-6 production, with secretion reduced in uninfected pigs fed with BBE, but tended to be enhanced in infected pigs." (PMID 35069576, 2021). "Infection of HSV-2 caused a significant reduction in HeLa cells and increased the gene expression of inflammatory cytokines TNFα, IL6, IL8 and IP10." (PMID 34943765, 2021). "In response to the infection, the acute increase of different circulating pro‐inflammatory cytokines (including IL‐6, IL‐1, TNF‐ α, and interferon) is correlated directly with an unfavorable prognosis in COVID‐19." (PMID 33512742, 2021). "Certain protective aspects of IL-6 influence leukocyte migration such as prevention of neutrophil accumulation at the site of inflammation/infection." (PMID 34858437, 2021). "In particular, levels of IL-6 and KC peaked to similar levels within the first 8 h, later declining to background levels 48 after infection in both groups of mice." (PMID 33622714, 2021).
infection (continued). "Peroxisome proliferator activator receptor gamma (PPARγ) is an important regulator of the macrophage pro-inflammatory responses to infection regulating TNFα and IL-6 production." (PMID 34054509, 2021). "In IL-6–/– mice, the rate of parasite killing and infection control was higher as compared to WT mice." (PMID 33680991, 2021). "Conversely, after 24 h, IL-6 levels had decreased below the TNC+/+ levels (P = 0.04), while IL-6 levels were low in both genotypes at 48 h after infection (P = 0.64)." (PMID 34319124, 2021). "Infection with either of the four strains resulted in an up-regulation of IL-6, IL-10, IFN-λ, IFN-γ, IP-10, MX-2, and TNF-α expression in the range of 10- to 1000-fold compared to non-infected hamsters." (PMID 34049240, 2021). "In the acute phase of an infection, plasma levels of inflammatory cytokines such as TNFα, IL-1β, and IL-6 sharply increase, followed by enhanced secretion of proteins belonging to the family of acute-phase proteins." (PMID 34047814, 2021). "Upon infection, maternal immune activation produces significant amounts of pro-inflammatory cytokines, many of which including IL6, TNFα, IL10 and IL1β can be detected in the fetal brain." (PMID 34858132, 2021). "To better investigate miR-34a and IL6 relationship in HASMCs, we stably overexpressed miR-34a in HASMCs isolated from the 22- and 43-year-old donors by infection with pMIRNA1 (CTRL) or pMIRH34a (miR-34a) lentivirus." (PMID 32585876, 2020). "WT levels of TNF-α, IL-1, and IL-6 increased robustly in WT pups following infection, while TNF-α and IL-6 expression was significantly reduced in IL-27Rα−/− pups." (PMID 31818960, 2020). "As expected, all infections resulted in a significant increase in pro-inflammatory status as evidenced by increased expression of iNOS, IL-6, and TNF-α." (PMID 32370298, 2020). "PKCδ deficiency enhances the expression of IL-6 and TNF-α in macrophages and increases the IL-6 production in spleen tissue after infection of Listeria monocytogenes, which suggests that PKCδ can attenuate inflammatory response and the macrophages activation." (PMID 32390869, 2020). "Increased U frequency in the SARS-CoV-2 genome enhances TNF-α and IL-6 production in our pseudo-infection model." (PMID 33082451, 2020). "There were significant differences in IL-6 s of BALFs from patients between mild cases and severe cases, MP single infection group and MP mixed infection group, and low MP DNA loads group and high MP DNA loads group, respectively (P < 0.05)." (PMID 32393186, 2020). "At 24 h post-infection, the mRNA expression of pro-inflammatory cytokines (i.e., Tnf-α, Il-1β, and Il-6) in both the cerebral cortex and hippocampus homogenates was evaluated by RT-PCR." (PMID 32676082, 2020). "Two days after infection (day 2), the levels of pro-inflammatory cytokines IL-6, TNF-α, and IL-1β were significantly higher in the group ZE compared with the group ST." (PMID 32486242, 2020). "In paw tissue from infected mice after infection, we found a significantly increased level of the principal proinflammatory cytokines IL-1β, IL-6, and TNF-α, while treatment with artesunate significantly reduced the levels of these cytokines." (PMID 32230725, 2020). "In fact, consistently elevated IL-6 levels were observed in an EV-A71 infection neonatal mouse model resulting in severe damage to numerous organs including the brain pointing to EV infected astrocytes as contributors to CNS damage." (PMID 32328043, 2020). "Severe systemic inflammation upon infection leads to the production of excessive pro-inflammatory cytokines like IL-6, IFNγ, and TNFα." (PMID 33182754, 2020). "In the spinal cord, WT-infected mice had higher levels of Il6, Tnf, Ccl2, and Ccl5 mRNAs at 2 or 4 days after infection, while Il1β was highest in Y114A at 2 and 6 days (P < 0.01 versus G32S, P < 0.0001 versus Y114A)." (PMID 32047134, 2020).
infection (continued). "The IL-6 was significantly down regulated in the treated cells compared to untreated cells after infection with SARS-CoV-2 at 6–8 h (p<0.05), and 12–36 h (p<0.001)." (PMID 33206688, 2020). "Sixteen hours post-infection, the frequencies of IL-6- and TNF-α-positive cells correlated with the dose of the virus." (PMID 33261178, 2020). "As shown in the present study, P. gingivalis infection alone can lead to robust pro-inflammatory IL-6 secretion by the GECs in earlier stages of infection." (PMID 32419582, 2020). "IL-6, when promptly and transiently produced in response to infections and tissue injuries, contributes to host defense through the stimulation of acute phase responses or immune reactions." (PMID 32425950, 2020). "The cell-free supernatants after post-infection were analysed for the expression of pro-inflammatory cytokines IL-1β, IL-6 and TNF-α and anti-inflammatory cytokines IL-10, IL-12p40, IL-12p70 and IL-4." (PMID 32295519, 2020). "Significant upregulation of IL-6 was observed at 24 h (p < 0.0001) in pH1N1-alone infections, and at 8 and 24 h (p = 0.0303 and p < 0.0001, respectively) in pH1N1-MRSA coinfections." (PMID 33202895, 2020). "IL-6 is the target for therapy with tocilizumab, a monoclonal antibody that has demonstrated efficacy in severe infections and is in trial to be approved against Sars-CoV-2." (PMID 32635302, 2020). "Although the production of both cytokines in IFNAR-blocked BMMCs was lower than that of IFNAR−/− cells, it was still significantly higher than IFNAR-intact cells at 20 h post-infection (9.30% ± 0.79% for IL-6 and 14.75% ± 1.20% for TNF-α)." (PMID 33261178, 2020). "The levels of CRP, Fer, PCT, and IL-6, an acute phase protein, increase in the body immediately in response to infection or tissue damage." (PMID 33537326, 2020). "As a result, the expressions of NF-κB, IL-1β, and IL-6 in SEECs were increased after infection with E. coli, and there was a dose-dependent effect when the MOI was beneath 5:1." (PMID 32426380, 2020). "In context to immune regulation upon infection, miR-30e was found to significantly induce the expression of IL6 both at mRNA and protein levels as quantified by qRT-PCR and ELISA in presence of bacterial infection in HeLa cells compared to control miR-NC1." (PMID 33585275, 2020). "To further study the effect of PKK depletion on lung inflammation after infection, we measured the levels of cytokines (TNFα, IL‐1β, IL‐6) and chemokines (CXCL1, CXCL2) in lung homogenates." (PMID 31595971, 2020). "IL-6 production and secretion by mouse and human lung epithelial cells is triggered during infection with influenza virus and other viruses such coronavirus." (PMID 33193346, 2020). "Pro-inflammatory cytokines like IL-1α, IL-1β, IL-6, and IL-8 have been noted for their roles in early infection response, producing a warning signal of pathogen invasion, and this response was present in septic TKR tissues." (PMID 32867801, 2020). "We also found that the levels of IL-6 significantly decreased (P = 0.0076, P = 0.0043) in the blood of mice administered with pasteurized A. muciniphila at 5 days post-infection." (PMID 33603716, 2020). "The author concluded the CRP and IL-6 appears to be the most helpful combination for distinguishing between aseptic loosening and low-grade infection." (PMID 33008442, 2020). "Many inflammatory cytokines and chemokines such as IL-6, IL-1β, IL-8, CCL8, CXCL9, CXCL16, MCP-1 and IP-10 and immunosuppressive cytokines such as IL-10 are elevated in both infections and associate with clinical disease severity." (PMID 33199778, 2020). "The Salmonella-challenged treatment (T2) follows the previously documented studies: IL-6 and IL-1β are highly upregulated on day 2 and dramatically reduced by day 4 post-infection." (PMID 33260977, 2020). "Chronic inflammation is also a simple marker of other diseases, and circulating levels of CRP or IL-6 are easily influenced by infection and the anti-infectious medication use." (PMID 33202561, 2020).
infection (continued). "Serum levels of IL-6 were significantly increased eight and 13 days post infection (dpi), while intestinal IL-6 levels showed a trend to significant increase 8 dpi." (PMID 32283818, 2020). "CSFV Shimen infection has a significant effect on the transcription and translation of IL6 in macrophages." (PMID 32110485, 2020). "Treatment with proteasome inhibitor significantly inhibited the release of IL-1, IL-6, TNFα, MIP-1β (i.e. CCL4), and KC (i.e. CXCL1) at their peak time-points in Balb/c mice after infection with the highly pathogenic avian H5N1 influenza A virus." (PMID 33362782, 2020). "The keratinocytes secreted an increasing amount of the pro-inflammatory cytokines IL-6 and IL-1α 24 h and 48 h after infection with S. aureus." (PMID 33302597, 2020). "IL-6 is generated early in the infection as a result of innate, MyD88-dependent pathway, immune receptor activation by endogenous viral proteins." (PMID 32961074, 2020). "Cytokines such as IL-6, IL-1β, IL-17 and TNF-a have been associated with exacerbation of the infection, with TNF-a, an important NO inducer, being particularly significant in mucosal leishmaniasis evolution." (PMID 32321156, 2020). "As a novel finding in this study, koalas with two exogenous KoRV subtypes (KoRV-B and KoRV-C) in addition to the endogenous KoRV subtype (KoRV-A) showed significantly higher expression of IL-6 in PBMCs than koalas with only the endogenous infection." (PMID 33316950, 2020). "Prompt recognition of bacterial pathogens is paramount in the defense against infection, and, among the mechanisms that initiate the immune cascade, IL-6 plays a central role." (PMID 32308976, 2020). "Both BEAS-2B and hAEC cells showed increased IL-6 expression on both mRNA and protein levels upon AdV 7 infection, and such increase was more profound in BEAS-2B cells than in hAEC cells." (PMID 33072092, 2020). "While, IL-6 has a protective role in many infections, it can be the key to the maintenance of chronic inflammatory conditions." (PMID 32542025, 2020). "Exposure of DCs to this infection results in an increased release of IL-6 and IL-10 with STAT3 phosphorylation." (PMID 33028328, 2020). "The only statistically significant differences were different monocyte counts (higher at T1, p = 0.05, and lower at T2, p < 0.05), and higher IL-6 values at T2 (p = 0.05) in patients with an infection." (PMID 32377009, 2020). "After 90 days of infection, increased IL-6 and IFN-γ production was seen in the spleen, as well as higher frequencies of follicular and plasmacytoid dendritic cells." (PMID 32351510, 2020). "After secondary infection, transcript production for iNOS, IL-6, and IL-10 was increased while Il4 was strongly reduced in sham and CLP-operated mice." (PMID 32425929, 2020). "This is likely a result of increasing concentrations of pyrogenic pro-inflammatory cytokines, such as TNF-α, IL-1, and IL-6, which affect the thermoregulatory centers of the brain in response to an infection." (PMID 33123678, 2020). "Several studies have shown that infection of BECs with Aspergillus fumigatus leads to the release of pro-inflammatory cytokines, mostly IL-6, IL-8, or tumor necrosis factor-α provided that the infection time is more than 6 h and allows conidia germination." (PMID 32528481, 2020). "RSV infections are characterized by the rapid (18–24 h following infection) and transient induction of early innate immune mediators such as type I IFNs, IL-6, and TNF-α." (PMID 33123150, 2020). "The mRNA levels of Tnf, Il6, and Il1b were significantly increased in BMDMs from Ppara-/- mice, compared with Ppara+/+ mice, at 6 h after Mabc infection." (PMID 32155958, 2020). "First, an obvious increase in the levels of IFN-γ, IL-6, IL-1β, IL-1Ra, IL-18, IL-5, IL-8 was detected in the early (3 dpi) stage of infection, indicating the activation of innate immune responses, such as monocytes and NK cells." (PMID 33180882, 2020).